MACC1 (MET transcriptional regulator MACC1)
Diseases named in the same sentence as MACC1 in open-access papers (continued):
Sharing a sentence is not in itself a finding about the gene and the disease.
tumor (continued). "During tumor growth, downregulation of MACC1 significantly inhibited tumor volume, resulting in reduced tumor weight and size, indicating that MACC1 down-regulation suppresses tumor growth (P < 0.01)." (PMID 40354443, 2025). "Targeting the HGF/c-Met axis, along with MACC1, offers a promising strategy for inhibiting tumor progression." (PMID 40354443, 2025). "Our findings demonstrate that MACC1 knockdown effectively suppresses tumor migration, invasion, and proliferation, highlighting its functional importance in EC progression." (PMID 40354443, 2025). "In vivo, daily intraperitoneal injections of lovastatin (10 mg/kg for three weeks) in mice with MACC1-overexpressing CRC xenografts significantly suppressed tumor growth and liver metastases." (PMID 40807057, 2025). "In xenografted, patient-derived and transgenic mouse models, MACC1 induces tumor initiation and progression, as well as liver and lung metastases." (PMID 38339354, 2024). "MACC1, in particular, has been identified as one target initiated through the tumor-promoting effects of two major regulators: the cytokines tumor necrosis factor (TNF)-α and IFN-γ." (PMID 38611008, 2024). "This understanding guides ongoing research into MACC1-based therapeutic strategies to inhibit tumor growth and metastasis." (PMID 39399490, 2024). "Tumorigenesis and increased tumor volumes were observed in those mice transplanted with CD44-high/CD166+ cells also showing high MACC1 and LGR5 levels (vs. CD44-low/CD166+ cells)." (PMID 38339354, 2024). "Further, we investigated the effect of MACC1 knockdown on phenotypical stemness features and observed a clearly reduced tumor sphere formation." (PMID 38339354, 2024). "Next, we measured the MACC1 protein levels in tumour samples and found that the in vivo treatment of SS-b2 significantly downregulated MACC1 and c-Met expression and Akt protein phosphorylation, while it enhanced the phosphorylation of BAD." (PMID 39544485, 2024). "In this study, a novel therapeutic strategy was devised to target TM4SF5-expressing cancer cells and suppress MACC-1 function using microRNA-encapsulated Ex, demonstrating promising anti-tumor effects both in vitro and in vivo." (PMID 39273182, 2024). "While the precise mechanisms are still being elucidated, MACC1 exerts multiple signaling effects in tumor cells including Erk and Akt activation." (PMID 38396744, 2024). "In summary, these results indicated that the affection of MACC1/c-Met/Akt signalling and the inhibition of proliferation resulting from SS-b2 contribute to the repression of tumour growth in vivo." (PMID 39544485, 2024). "MACC1 expression was obviously decreased in tumor tissues analyzed by IHC, confirming the silencing efficacy." (PMID 39695175, 2024). "The overexpressing efficacy of MACC1 in the tumor tissues was confirmed by IHC analysis simultaneously." (PMID 39695175, 2024). "Therein, we highlight the signaling pathways and secreted factors influenced by MACC1 as well as their effects on the infiltration and anti-tumor function of immune cells." (PMID 38611008, 2024). "Age, N stage, and pTNM stage were identified as risk factors, whereas tumor grade, and B3GNT3, MACC1, NELL2, and USH1G were identified as protective variables." (PMID 38818465, 2024). "Here, we explored the molecular mechanisms by which MACC1 regulates stemness and the CSC-associated invasive phenotype based on patient-derived tumor organoids (PDOs), patient-derived xenografts (PDXs) and human CRC cell lines." (PMID 38339354, 2024). "Their group identified MACC1 as a player in driving an aggressive disease phenotype in the primary tumour and was first to find a therapeutic targeting MACC1." (PMID 39140283, 2024). "One such process that to date remains only vaguely comprehended is in what manner MACC1 is involved in regulating how tumor cells interact with their environment, and specifically with close-by immune cells." (PMID 38611008, 2024).
tumor (continued). "Taken together, we have demonstrated that MACC1 shapes the environment for tumor cells to promote the formation of metastasis by mediating various strategies relevant to immune escape mechanisms of cancer cells." (PMID 38611008, 2024). "Here, we report for the first time the link of MACC1, which is known to induce tumor initiation, progression and metastasis, with stemness by transcriptional expression activation of LGR5, a central stemness gene." (PMID 38339354, 2024). "The tumor-intrinsic expression of MACC1 is relevant for the sensitization to death receptor-mediated apoptosis via Fas/FasL." (PMID 38611008, 2024). "Several studies have identified correlations between MACC1 expression levels and the infiltration of immune cells into the tumor surrounding areas." (PMID 38611008, 2024). "MACC1 levels analyzed from tumor tissue or liquid biopsies can be used to determine the individual metastatic risk and predict patient survival and therapy outcomes." (PMID 38611008, 2024). "More than 20 solid cancer types, including BC, have MACC1 identified as a crucial actor and biomarker for tumor growth and metastasis." (PMID 36979146, 2023). "We have previously shown that high MACC1 expression, either endogenous or by forced overexpression, induced tumor initiation, progression and metastasis in mice." (PMID 38144523, 2023). "MACC1 is a potentially effective therapeutic target for solid tumors’ anti-tumor and anti-metastatic intervention techniques." (PMID 36979146, 2023). "Multiple studies have shown that the tumor process mediated by the AKT signal transduction pathway was regulated by MACC1." (PMID 36979146, 2023). "Studies have revealed that MACC1 shields metastasis from immunological disruption by modifying the tumor microenvironment (TME)." (PMID 36979146, 2023). "We identified an important, dual function of GIPC1 - as protein interaction partner and as transcription factor of MACC1 – for tumor progression and cancer metastasis." (PMID 38144523, 2023). "Studies have some limitations, such as the relatively small number of patients studied and the fact that the majority of serum MACC1 is derived from tumor tissue." (PMID 36979146, 2023). "In conclusions, we identified a novel, dual function of GIPC1 - as protein interaction partner and as transcription factor of MACC1 – for tumor progression and cancer metastasis." (PMID 38144523, 2023). "MACC1 is a new immunotherapy target that can be exploited as a predictor of the immune response in tumor patients." (PMID 36979146, 2023). "Statins, especially Lovastatin, Fluvastatin and Atorvastatin, have the potential to inhibit MACC1 activity and thereby reduce proliferation and invasion of tumor cells." (PMID 37627117, 2023). "It was shown that the MACC1 expression level in tumor specimens is a stage-independent prognostic biomarker for metastasis formation and thus metastasis-free survival." (PMID 36674695, 2023). "Here, we will summarize the current knowledge about MACC1-induced tumor cell migration with a special focus on the cytoskeletal and adhesive systems." (PMID 37051546, 2023). "A pan-cancer database analysis of MACC1 in 33 cancer types generated a consensus list of 1,896 genes correlating with MACC1 in at least half of the tumor entities." (PMID 37051546, 2023). "It is clear that MACC1 can influence immune cell infiltration into the tumor microenvironment, facilitate tumor cell immune evasion, and serve as a solid independent prognostic indicator for BC." (PMID 36979146, 2023). "MACC1 is a tumor-initiating and metastasis-promoting oncogene, whereas S100A4 has not been shown to initiate tumor formation but can, nevertheless, promote malignant tumor growth and metastasis formation." (PMID 36674695, 2023). "The expression of MACC1 in diverse tumor types and its method of involvement in carcinogenesis and development have been the subject of an increasing number of studies in recent years." (PMID 36979146, 2023).
tumor (continued). "GIPC1 suppression reduced tumor growth and metastasis in mice intrasplenically transplanted with MACC1-overexpressing CRC cells." (PMID 38144523, 2023). "In the few years since its discovery, MACC1 has been demonstrated to be a very promising predictive biomarker in a multitude of tumor entities because it induces migration and proliferation among others." (PMID 37051546, 2023). "Looking further downstream, MACC1 was frequently found to induce a mesenchymal phenotype in multiple tumor types, through the measurement of EMT markers, such as increased expression of vimentin and N-cadherin and reduced expression of E-cadherin." (PMID 37051546, 2023). "MACC1 promotes the immune escape of BC cells by affecting the infiltration of immune cells in the tumor microenvironment." (PMID 36979146, 2023). "Since MACC1 is involved in numerous biological processes inside and outside BC cells, it is a key player in the tumor microenvironment." (PMID 36979146, 2023). "In recent years, metastasis associated in colon cancer 1 (MACC1) was identified as a promising biomarker and drug target, as it is promoting tumor migration, initiation, proliferation, and others in a multitude of solid cancers." (PMID 37051546, 2023). "We aimed to confirm that MACC1 expression was dependent on tumor genetic background on a larger scale." (PMID 35406521, 2022). "Within the primary tumor cohort, the subgroup “MACC1 and S100A4 high” experienced the shortest MFS, while the subgroup “MACC1 and S100A4 low” showed the longest MFS (median follow up: 167.2 months; median MFS of 69 and 131 months, respectively; p < 0.0001)." (PMID 36008464, 2022). "Correlatively the MACC1-dependent effect of saffron is restricted and cannot entirely inhibit the tumor-promoting and metastasis-leading effect of MACC1." (PMID 36432477, 2022). "As expected, the TCGA data showed that MACC1 was highly expressed in PC tissues compared to normal tissues and was upregulated in multiple human tumor types." (PMID 36333284, 2022). "Tumor volume was monitored every four days, and tumor tissue in the MACC1 OE group grew much faster than that in the vector group (P < 0.01)." (PMID 35874635, 2022). "MACC1 was found to express more highly in CC tissues in comparison with corresponding non-tumor tissues at both mRNA and protein levels." (PMID 34939526, 2022). "Of note, the analysis also revealed higher variability of MACC1 expression among COAD tumor samples, with notably some outliers with very low values (<8) (COAD ranged from 5.58 to 12.55; READ: 8.99 to 13.07)." (PMID 35406521, 2022). "Two other authors analyzed the role of MACC1 in a subcutaneous xenograft model, with a measurable large tumor size at the experimental end in the MACC1 overexpressing group." (PMID 35406545, 2022). "For example, exosomal circ-PDE8A has been showed association with tumor progression and lymphatic invasion in pancreatic ductal adenocarcinoma (PDAC) via the miR338/MACC1/MET pathway." (PMID 35505392, 2022). "Compared to the tumor tissues in the MACC1 OE group, the tumors in the vector group had a significantly smaller size (P < 0.01)." (PMID 35874635, 2022). "MACC1 promotes tumor development by regulating the HGF/c-Met pathway and microtubule stability and is a key regulator of the c-Met pathway." (PMID 35242498, 2022). "The upregulation of MACC1 mediated by MACC1-AS1 finally triggers MACC1-mediated metabolic plasticity, which enhances glycolysis and antioxidant capacity to promote tumor progression of GC." (PMID 35625948, 2022). "In summary, the results showed that selumetinib treatment inhibited MACC1-induced metastasis formation in the AGE/S FLO-1 tumor model in vivo." (PMID 35406545, 2022). "They conclude that copy number gain and overexpression of MACC1 correlated with pathologic attributes of tumor evolution in the context of liver metastases from CRC." (PMID 35406521, 2022).
tumor (continued). "IHC results from the Human Protein Atlas indicated that the MACC1 protein was upregulated in the CC tissues with respect to that in the non-tumor tissues." (PMID 34939526, 2022). "By removing metastatic status from the analysis, we showed that high MACC1 expression and high tumor size were independent predictors of reduced DFS (p = 0.02 and p = 0.03, respectively)." (PMID 35406521, 2022). "In conclusion, this study we have demonstrated that MACC1 is overexpressed in several types of human cancers and that MACC1 overexpression correlates with poor prognosis and increased tumor immune cell infiltration in patients with COAD." (PMID 36545127, 2022). "For CRC, we reported that pro-inflammatory TNF-α and IFN-γ promote tumor growth and metastasis via induction of MACC1." (PMID 35406521, 2022). "The potential role of MACC1 in tumor immunity was further assessed by evaluating the correlation between MACC1 mRNA expression and biomarkers of immune cells in COAD using the GEPIA2 database." (PMID 36545127, 2022). "Beside the prognostic role of MACC1 in several tumor entities, it harbors the potential as a druggable target in cancer therapy." (PMID 35406545, 2022). "Next, we were interested if there is an overlap of tumour-promoting target genes of MACC1 and S100P, when ectopically expressed in SW480 cells." (PMID 35597866, 2022). "High MACC1 expression levels, determined in the primary tumor or in cancer patient blood, predict tumor aggressiveness and metastasis formation linked to shorter patient survival." (PMID 35406521, 2022). "In pancreatic cancer, the tumor-released exosomal circRNA PDE8A promotes aggressive growth through the miR-338/MACC1/MET pathway." (PMID 35505392, 2022). "A comparative study demonstrated that inhibiting MACC1 expression restricts tumor progression and metastasis." (PMID 36333284, 2022). "In contrast, we observed high MACC1 and elevated S100P IHC staining in tumour sections from CRC patients who suffered from metachronous metastasis." (PMID 35597866, 2022). "MACC1 induces cell proliferation, dissemination, migration, and invasion in vitro, as well as tumor progression and metastasis formation in vivo." (PMID 35406545, 2022). "This study provides evidence to target MACC1 via natural products to establish new treatment opportunities for the treatment of especially MACC1-driven tumor progression and metastasis." (PMID 36432477, 2022). "Analysis of MACC1 expression in 21 tumor cells lines in the CCLE database showed that MACC1 was highly expressed in most cell lines." (PMID 36545127, 2022). "Collectively, these data indicated that MACC1 acts as an oncoprotein in PC cells to facilitate tumor metastasis." (PMID 36333284, 2022). "In this tumor subset, we validated that high MACC1 expression correlated with increased SCNA and occur preferentially in tumors located in the distal part of the colon." (PMID 35406521, 2022). "MACC1 was next analyzed in the context of the transcriptomic-based consensus molecular subtypes (CMSs) which were established based on the tumor gene expression." (PMID 35406521, 2022). "In this study, we investigated the effect of the natural compound curcumin on reversing the tumor-promoting effect of MACC1 by reducing its expression." (PMID 36432477, 2022). "We examined the expression levels of proliferation and migration-related proteins in the tumor tissues between the vector group and the MACC1 OE group by western blot." (PMID 35874635, 2022). "MACC1 regulates key processes during tumor progression such as proliferation, migration, invasiveness, and metastasis formation in xenografted and transgenic mice." (PMID 35740524, 2022). "From a mechanistic point of view, MACC1 induces the activation of the HGF/c-Met axis in multiple tumor entities." (PMID 35740524, 2022). "In this study, we have investigated the effect of one of the promising natural products, curcumin, on MACC1 expression and MACC1-induced tumor-promoting pathways." (PMID 36432477, 2022).
tumor (continued). "Statistical analysis showed that the high expression of MACC1 was related to tumor size (P = 0.02, P < 0.05)." (PMID 35242498, 2022). "MACC1 has been established by us and many other groups as crucial for tumor development and metastasis." (PMID 35740524, 2022). "With 79.3% MACC1-positive tumor samples, our cohort has a higher rate of MACC1-expressing samples compared to the studies of Asian populations (mean 57.8% (34.9–80.6))." (PMID 35406545, 2022). "The association of MACC1 expression with patient DFS and OS was further assessed by multivariate analysis against tumor size and stage, nodal and metastatic status." (PMID 35406521, 2022). "Protein expression of MACC1 and S100P in the sections correlated significantly (N = 27) and we observed an increase of both MACC1 and S100P staining in tumour tissue with metachronous metastasis." (PMID 35597866, 2022). "To confirm these findings, we further explored the effects of the MACC1 gene on tumor growth in vivo and found that silencing MACC1 slightly impaired the growth of PC tumors; however, this difference not statistically significant." (PMID 36333284, 2022). "Since MACC1 has been reported to be involved in tumor immunity, the correlation between MACC1 mRNA expression and immune cell infiltration level was evaluated." (PMID 36545127, 2022). "In vivo, MACC1 increases tumor cell proliferation and motility, supports cell survival, and regulates metabolism, thereby promoting metastasis." (PMID 36545127, 2022). "Elevated ORAI1 and STIM1 expression upregulated MACC1 expression and promoted tumor cell proliferation, metabolism, migration, and invasion in human gastric cancer." (PMID 35406521, 2022). "The results indicated that, after the high expression of MACC1, tumor invasion and proliferation were significantly promoted in vivo and in vitro." (PMID 35874635, 2022). "In vivo, the efficacy of selumetinib on tumor growths and metastases of MACC1-overexpressing FLO-1 cells xenografted intrasplenically in NOG mice was tested." (PMID 35406545, 2022). "Expression and correlation analyses showed that hsa-miR-642a-5p was the most likely tumor-suppressive miRNA targeting MACC1." (PMID 36545127, 2022). "Here, we used molecular approach to demonstrate that SPINT1 serves as a downstream signaling protein of MACC1, participating in tumor genesis and progression through HGF/c‐Met signaling pathway." (PMID 33751856, 2021). "Our data reveals that GLUT-1 and MACC1 has a prognostic capacity for stratified tumor pathological factors (T status and differentiated degree)." (PMID 33750337, 2021). "The current study was extended to investigate the correlation between MACC1 expression and CD163+ tumor-associated macrophages, CD56+ natural killer cells, and CD8+ cytotoxic T lymphocytes within BC tumor microenvironment." (PMID 34577857, 2021). "Overexpression of MACC1 leads to progression and metastasis of many solid tumor entities, by promoting cell proliferation and migration, and thereby enhancing tumor growth and invasion." (PMID 33469705, 2021). "MACC1 is an important transcription factor involved in EMT that promotes tumor cell migration and distant metastasis." (PMID 33827418, 2021). "As GLUT-1 and MACC1 were a promising biomarker to distinguish tumor progression and malignant degree." (PMID 33750337, 2021). "We investigated clinically applicable MEK1 inhibitors on MACC1-induced tumor growth and metastasis in xenografted mice over time by in vivo bioluminescence imaging." (PMID 34247190, 2021). "To assess, if the MACC1-dependent stabilization of TfR and its faster recycling leads to alterations of iron homeostasis, we stained tissue sections of cell line-derived tumor sections with Perls’ Prussian blue solution." (PMID 33469705, 2021). "This affirms MACC1 as a decisive driver for tumor growth and metastasis, but also as a therapeutic target to restrict cancer progression and metastasis." (PMID 34247190, 2021).